EMX2 (empty spiracles homeobox 2)
Diseases named in the same sentence as EMX2 in open-access papers (continued):
Sharing a sentence is not in itself a finding about the gene and the disease.
endometrial cancer (4 papers, 2008 to 2023). Primary or metastatic malignant neoplasm involving the endometrium (mucous membrane that lines the endometrial cavity). "EMX2 downregulation has been considered as a critical issue in the carcinogenesis of endometrial cancer and contributes to cancer progression." (PMID 30576338, 2018). "In addition, PBX2 and HOXA10 interactions with EMX2 were demonstrated in endometrial cancer cell lines." (PMID 18973687, 2008).
endometriosis (4 papers, 2013 to 2022). The growth of functional endometrial tissue in anatomic sites outside the uterine body. "Expression of empty spiracles homolog 2 (EMX2) was elevated during the implantation window in endometriosis patients and associated with implantation failure." (PMID 30104541, 2018). "In connection with diminished expression of HOXA10 in the endometriosis, the increased level of endometrial mRNA EMX2 is found during the peri-implantation period, which may result in the aberrant course of the embryo’s implantation process." (PMID 35409163, 2022).
glioma (4 papers, 2016 to 2022). A benign or malignant brain and spinal cord tumor that arises from glial cells (astrocytes, oligodendrocytes, ependymal cells). "In agreement with the results obtained with glioma cell lines, EMX2 was significantly repressed in tumour samples compared to normal individuals (P < 0.0001), whilst numerous HOX genes across all clusters showed higher levels in patients." (PMID 31468686, 2019). "Conversely, expression data from the cancer cell line encyclopaedia database (CCLE) showed widespread repression of EMX2 in a large panel of glioma cell lines, whilst aberrant expression of HOXB9 was detected in 19 lines (RPKM ≥ 5)." (PMID 31468686, 2019). "As EMX2 is reported to play a role in carcinogenesis, we investigated the impact of EMX2 overexpression in glioma-related cell lines." (PMID 30514244, 2018). "Altogether, these results strongly support an EZH2‐mediated EMX2‐HOX switch in glioma." (PMID 31468686, 2019). "We conclude that silencing of EMX2 by EZH2 is required for maintenance of tumorigenic potential by GBM cells and is a major mechanism underpinning the pathological role of EZH2 in glioma." (PMID 31468686, 2019). "In addition, both low and high‐grade glioma showed inverse correlation between EZH2 and EMX2 mRNA levels (Fig EV4C)." (PMID 31468686, 2019). "EZH2 and EMX2 levels showed a significant anti‐correlation in multiple glioma patient datasets, supporting the hypothesis that EZH2 represses EMX2 in patients (and EV4A and C)." (PMID 31468686, 2019).
infertile (3 papers, 2017 to 2021). "In fact, a concomitant increase of EMX2 and Ten-1 was recently reported in the endometrium of infertile patients with Müllerian duct anomalies, and the authors suggested a role for EMX2-mediated upregulation of Ten1 in this pathology." (PMID 28472127, 2017). "HOXA10, EMX2, TENM1 mRNA and protein expression levels differ significantly in mid-secretory endometrium in infertile women with a Mullerian duct anomaly compared with controls." (PMID 31844537, 2019).
lung adenocarcinoma (3 papers, 2012 to 2018). A carcinoma that arises from the lung and is characterized by the presence of malignant glandular epithelial cells. "More recently, we have demonstrated epigenetic silencing of EMX2 expression in lung adenocarcinomas and its association with poor clinical outcomes in early stage lung adenocarcinoma patients." (PMID 26132438, 2015). "Together with our observations that high EMX2 expression levels were significantly associated with improved overall survival in early stage lung adenocarcinomas, it appears that EMX2 may play similar roles in both subtypes of human NSCLC." (PMID 26132438, 2015). "In addition, silencing EMX2 has been suggested to aberrantly activate Wnt signaling in lung adenocarcinoma, and some EMT markers are downstream targets of Wnt pathway, such as E-cadherin." (PMID 26132438, 2015). "Decreased EMX2 mRNA expression is also a valuable prognostic marker of shorter OS and RFS in patients with lung adenocarcinoma." (PMID 30576338, 2018). "Our results demonstrated a significant decrease in EMX2 expression in primary lung SCC tissue samples when compared to their adjacent normal tissues, similar to that observed in lung adenocarcinomas." (PMID 26132438, 2015). "Preserved EMX2 expression might also have potential prognostic value in terms of overall survival (OS) and recurrence-free survival (RFS) in lung adenocarcinoma and lung squamous cell carcinoma." (PMID 30576338, 2018).
breast carcinoma (2 papers, 2017 to 2025). "Concomitant expression of Ten-4 and EMX2 was indeed observed in SHSY5Y neuroblastoma and in ovarian cancer cells, whereas Ten-2 and EMX2 showed an inverse expression pattern in HeLa and in breast cancer cells." (PMID 28472127, 2017). "On the other hand, EMX2 expression was detected in half of ESCC and ovarian cancer cell lines but not in colon, stomach, or breast cancer cell lines, except for BT20." (PMID 40564092, 2025).
colorectal tumor (2 papers, 2017 to 2018). "Compared to corresponding healthy mucosa, colorectal tumor samples had decreased EMX2 expression levels." (PMID 28830374, 2017). "The expression of EMX2 transcripts was measured in paired normal mucosa and tumor tissue samples, revealing that EMX2 expression was significantly lower in colorectal tumor samples compared to their corresponding healthy mucosa." (PMID 28830374, 2017). "For this purpose, EMX2 transcript expression levels were assessed in 29 colorectal liver metastases from our tissue biobank, and EMX2 expression in metastases was compared to expression levels in primary colorectal tumors." (PMID 28830374, 2017). "In an attempt to further elucidate whether enhanced metastatic progression of colorectal tumors could indeed be attributable to expressional changes of EMX2, we examined the effects of EMX2 on the migratory potential of colorectal tumor cells in vitro." (PMID 28830374, 2017).
cortical dysplasia (2 papers, 2012 to 2024). "Previous studies showed that EMX2 expression was found to negatively regulate the Wnt pathway and loss of Emx2 function leads to ectopic expression of Wnt1 in the developing telencephalon and cortical dysplasia." (PMID 39628661, 2024). "EMX2 is found as a direct repressor of Wnt1 expression, and knocking-down of EMX2 gene induces ectopic expression of Wnt1 in the developing telencephalon and cortical dysplasia." (PMID 23029345, 2012).
endometrial tumor (2 papers, 2012 to 2022). "Namely, while survival analysis and immunohistochemistry are both consistent with literature data suggesting EMX2 as endometrial tumor suppressor, the EMX2high group of patients were found to have higher expression of CTNNB1 and FGFR2, two known oncogenes implicated in endometrial oncogenesis." (PMID 35361846, 2022). "It is also reported that EMX2 expression is abundant in normal endometrium of postmenopausal women but absent or reduced in endometrial tumors, and EMX2 levels are negatively correlated with proliferation." (PMID 23029345, 2012).
ependymoma (2 papers, 2007 to 2021). A WHO grade II, slow growing tumor of children and young adults, usually located intraventricularly. "Transcription factor EMX2′s upregulation is notably observed in supratentorial ependymomas." (PMID 34203272, 2021). "However, aberrant transcription factor activity such as empty spiracles homeobox 2 (EMX2), breakage of the adherence gene αE-Catenin at the apical cell junction, and deregulation of notch signaling pathways have been found to convert the RGC behavior and provoke ependymoma activity." (PMID 34203272, 2021).
leiomyosarcoma (2 papers, 2021). An uncommon, aggressive malignant smooth muscle neoplasm, usually occurring in post-menopausal women. "To explore the role of EMX, we first selected three different low-passage sarcoma cell lines from different tissues of origin; two sarcoma lines expressed low levels of EMX1 and EMX2, as models to study the effects of EMX overexpression: AA (leiomyosarcoma) and AW (liposarcoma)." (PMID 34016958, 2021).
Lung Squamous Cell Carcinomas (2 papers, 2015 to 2018). "Preserved EMX2 expression is significantly associated with higher chemo-sensitivity and better OS in patients with lung squamous cell carcinoma." (PMID 30576338, 2018).
Mayer-Rokitansky-Küster-Hauser Syndrome (2 papers, 2022 to 2023). "Of those, LHX1, EMX2 and the Hox genes have previously been associated with MRKH syndrome either by sequencing of patient blood or functional in vivo studies with animal models." (PMID 35394036, 2022).
melanoma (2 papers, 2021 to 2022). A malignant, usually aggressive tumor composed of atypical, neoplastic melanocytes. "Moreover, aberrant expression of EMX2 has been reported to be correlated with the development of cancer originated from melanocytes (a derivative of the neural crest), including melanoma and GBM." (PMID 35849030, 2022).
ovarian carcinoma (2 papers, 2017 to 2025). A malignant neoplasm originating from the surface ovarian epithelium. "As in ovarian cancer cell lines, we could detect Ten-4 and concomitant expression of EMX2 mRNA in all tissue samples examined, independent of their histology and malignant condition." (PMID 28472127, 2017).
sarcoma (2 papers, 2021). A usually aggressive malignant neoplasm of the soft tissue or bone. "The Wnt-EMX1/EMX2 relationship was validated in silico with sarcoma patient datasets, in vitro in primary derived sarcoma cell lines, and in vivo." (PMID 34364391, 2021). "In this way, the Wnt pathway was established as one of the pathways related to the action of the transcription factors EMX1/EMX2 in sarcoma tumorigenesis." (PMID 34364391, 2021). "Murine KO models of Emx1 or Emx2 have been used to validate the initiation and development of sarcomagenesis in sarcomas induced with wild or hemizygous levels of Emx1/Emx2." (PMID 34016958, 2021). "The results obtained in our cell model showed a reduction in stem cell characteristics when EMX1 or EMX2 was overexpressed in primary sarcoma cell lines." (PMID 34364391, 2021). "Our work showed that EMX1/EMX2 act as tumor suppressors in sarcomas by repressing the activity of stem cell regulatory genes (OCT4, SOX2, KLF4, MYC, NANOG, NES, and PROM1)." (PMID 34016958, 2021). "Together, these results indicate that the EMX1 and EMX2 genes negatively regulate these tumor-altering populations or cancer stem cells, acting as tumor suppressors in sarcoma." (PMID 34016958, 2021). "In this work, we showed that the canonical Wnt pathway is one of the mechanisms that explains the relationships of EMX1/EMX2 and stem cell genes in sarcoma." (PMID 34364391, 2021). "Comparing the control muscle tissues and the induced sarcoma, we observed the highest expression of the stem cell genes (Oct4, Sox2, Klf4, Myc, and Nanog) and aggresivity in the sarcomas induced in the Emx1 or Emx2 KO mice." (PMID 34016958, 2021). "Taken together, these results indicate that the EMX1 and EMX2 genes negatively regulate these tumor-remodeling populations or sarcoma stem cells, acting as tumor suppressors in sarcoma." (PMID 34364391, 2021). "The transcription factors EMX1 and EMX2 act as tumor suppressors in sarcomas in vitro and in vivo by decreasing the expression of genes regulating the properties of stem cells and the stem cell phenotype." (PMID 34016958, 2021). "The 3MC carcinogen-induced sarcomas have a more aggressive phenotype, increased infiltration into the femoral bone marrow, and reduced survival in the Emx1/Emx2 KO mice." (PMID 34016958, 2021). "Together with previous works, this study proposes that the expression of EMX1 and EMX2 is maintained in only cancer stem cells embedded in the tissue of origin of the sarcoma to maintain the quiescent state by repressing the Wnt pathway." (PMID 34364391, 2021). "Hypermethylation of the EMX1 and EMX2 promoters has been demonstrated in primary sarcoma lines." (PMID 34364391, 2021). "However, many sarcoma cells and tumors still maintain high levels of Emx1/Emx2 protein expression, suggesting the existence of other active pathways that bypass the tumor suppressive roles of EMX1/EMX2 in the initiation and progression of human sarcoma." (PMID 34364391, 2021). "However, the role of EMX1/EMX2 in the initiation and progression of human sarcoma, as a tumor model derived from the mesoderm and neural crest, has not yet been elucidated." (PMID 34016958, 2021). "In addition, the Emx1/Emx2 KO mice that are induced with sarcoma have decreased survival." (PMID 34016958, 2021). "All together, our results suggest that sarcoma self-renewing populations originate from neural or mesodermal precursors where EMX1 and/or EMX2 expression is silenced." (PMID 34016958, 2021). "In summary, our work showed that EMX1 and EMX2 act as tumor suppressors by suppressing the activity of stem cell regulatory genes (OCT4, KLF4, MYC, SOX2, NANOG, NES, and PROM1) in sarcoma." (PMID 34016958, 2021). "It is proposed that there is no or low expression of EMX1 and EMX2 in CSCs embedded in the tissue of origin of the sarcoma, allowing self-renewal of the tumor." (PMID 34016958, 2021).
sarcoma (continued). "In summary, our work shows that EMX1 and EMX2 act as tumor suppressors by suppressing the activity of stem cell regulatory genes (OSKM, NANOG, and PROM1) and effectors of the canonical Wnt pathway (CTNNB1, TCF4, MYC, WNT1 and CCDN1) in sarcoma." (PMID 34364391, 2021). "Therefore, we proceeded to characterize the activation state of the canonical Wnt pathway in primary sarcoma lines, including both EMX1 and EMX2 overexpression in AA and AW models and EMX1/EMX2 silencing in a BG model." (PMID 34364391, 2021). "To examine whether this effect was observed in sarcoma patients, we analyzed the correlations between the expression of EMX1/EMX2 and the expression of genes in signaling pathways regulating the phenotype of stem cells in thePerlman (N = 53), and head and neck tumors: TGCA (N = 520) datasets." (PMID 34364391, 2021).
bipolar disorder (1 paper, 2007). A disorder of the brain that causes unusual shifts in mood, energy, activity levels and the ability to carry out day-to-day tasks. "By qRT-PCR, PLSCR4 and EMX2 were significantly down-regulated in the schizophrenia suicide completers, but could not be confirmed in bipolar disorder." (PMID 17997842, 2007). "For schizophrenia, but not bipolar disorder, the differential expression of PLSCR4 and EMX2 was confirmed by RT-PCR." (PMID 17997842, 2007).
cholangiocarcinoma (1 paper, 2020). A carcinoma that arises from the intrahepatic biliary tree (intrahepatic cholangiocarcinoma) or from the junction, or adjacent to the junction, of the right and left hepatic ducts (hilar cholangiocarcinoma). "Of interest, EMX2OS and EMX2 showed significant correlations in all cancers, except cholangiocarcinoma." (PMID 33234727, 2020).
coloboma (1 paper, 2023). An abnormality in which a part of a structure in one or both eyes is missing. "Our study provides the first example of genetic targeting of EMX2 to cause developmental eye disorders, with microphthalmia and coloboma observed in Crispr/Cas9-generated mutant emx2 zebrafish." (PMID 36830662, 2023). "Macroscopic analysis revealed coloboma phenotypes in ephb3ab (47%, n = 15) and emx2 (27%, n = 15) targeted embryos." (PMID 36830662, 2023). "On review of the available literature, an apparent coloboma and ventral eye defect in a single image panel of an Emx2-/- mouse embryo at gestational stage E12.5 was noted, when OFC should be complete." (PMID 36830662, 2023). "All our conserved OFC genes, including the two novel MAC candidates, EMX2 and EPHB3, should be considered for further genetic and molecular analyses based on their gene expression profiles during eye development and the presence of coloboma and microphthalmia phenotypes in animal models." (PMID 36830662, 2023).
colorectal adenocarcinoma (1 paper, 2017). The most common type of colorectal carcinoma. "We aimed to assess the prognostic significance of EMX2 expression in stage III colorectal adenocarcinoma." (PMID 28830374, 2017).
dysplasia (1 paper, 2012). A usually neoplastic transformation of the cell, associated with altered architectural tissue patterns. "We found that EMX2 expression was significantly downregulated in dysplasia samples (P<0.05) and almost lost in cancer samples compared to that in adult normal stomach tissue, suggesting that EMX2 downregulation could occur at non-invasive precancerous stage." (PMID 23029345, 2012).
esophageal squamous cell carcinoma (1 paper, 2025). Esophageal squamous cell carcinoma (ESCC) is a type of esophageal carcinoma (EC) that can affect any part of the esophagus, but is usually located in the upper or middle third. "In this study, we focus on the expression profile and the prognostic significance of EMX2 in esophageal squamous cell carcinoma (ESCC)." (PMID 40564092, 2025). "The results confirmed our findings, demonstrating a significant association between higher EMX2 expression and relapse-free survival (RFS) in esophageal squamous cell carcinoma (ESCC) (n = 81, HR = 2.71, log-rank p = 0.042)." (PMID 40564092, 2025). "Our study highlights the critical role of Empty Spiracles Homeobox 2 (EMX2) in the progression and prognosis of esophageal squamous cell carcinoma (ESCC)." (PMID 40564092, 2025).
fibrosarcoma (1 paper, 2021). A malignant mesenchymal fibroblastic neoplasm affecting the soft tissue and bone. "We also selected a third line, with high expression of EMX1 and EMX2 (BG, mixoid fibrosarcoma) as the model to reduce the levels of both genes." (PMID 34016958, 2021).
male infertility (1 paper, 2024). The inability of the male to effect fertilization of an ovum after a specified period of unprotected intercourse. "Therefore, we hypothesize that the significant downregulation of DEGs (CFAP70, TTC29, CCDC40, DNAAF4, SYCE3, STK36, SPI1 and EMX2) in hybrid yellow catfish is the primary cause of male infertility or reduced fertility." (PMID 38891632, 2024).
malignant pleural mesothelioma (1 paper, 2018). A malignant neoplasm that arises from mesothelial cells in the pleura and shows a diffuse growth pattern. "EMX2 is a prognostic and predictive biomarker in malignant pleural mesothelioma." (PMID 30012197, 2018).
metastatic colorectal cancer (1 paper, 2017). "Taken together, these data suggest that down-regulation of EMX2 expression occurs in primary and, even more, in metastatic colorectal cancer." (PMID 28830374, 2017).
metastatic tumor (1 paper, 2017). "Down-regulation of EMX2 was associated with metastatic tumor progression and decreased overall survival." (PMID 28830374, 2017). "To investigate putative effects of down-regulated EMX2 expression on patient prognosis, we analyzed whether EMX2 transcript expression was associated with progression to metastatic disease." (PMID 28830374, 2017). "The functional assays in this study assessing tumor cell migration suggest a potential role for EMX2 in metastatic disease progression since EMX2 knockdown resulted in increased migration while restoration of EMX2 using an adenoviral vector led to decreased migration." (PMID 28830374, 2017).
microcephaly (1 paper, 2019). A congenital or acquired developmental disorder in which the circumference of the head is smaller than normal for the person's age and sex. "Together, our study links defects in the SNRPE gene to microcephaly and suggests that alterations of cellular splicing of specific mRNAs such as EMX2 results in the neurological phenotype of the disease." (PMID 31671093, 2019).
ovarian tumors (1 paper, 2017). "Although we did not measure absolute EMX2 levels, it should be examined if reductions in EMX2 parallel those of Ten-4 in ovarian tumors and underlie potential resistance mechanisms to this drug." (PMID 28472127, 2017).